PER1 (period circadian regulator 1)
Diseases named in the same sentence as PER1 in open-access papers (continued):
Sharing a sentence is not in itself a finding about the gene and the disease.
breast carcinoma (continued). "Downregulations of PER1, PER2, or PER3 have been observed in various cancers, including oral squamous cell carcinoma, head and neck squamous cell carcinoma, colorectal cancer, breast cancer, ovarian cancer, melanoma, and hematological malignancies." (PMID 38813085, 2024). "In their study, western blotting showed that the expression of PER1 and PER2 decreased in the rhythm group, whereas the expression of breast carcinoma amplified sequence 4 (BCAS4), tubulin beta-2B chain (TUBB2B), and Roof Plate-Specific Spondin-4 (RSPO4) increased in the breast cancer group." (PMID 38074657, 2023). "Similarly, according to clinicopathological features, PER1, PER2, and PER3 are obviously methylated in breast cancer patients." (PMID 36385012, 2022). "Based on TCGA analysis and the defined criteria, we identified ten potential candidate genes of which SPAG6, PER1 and NKX2-6 proved suitable for early breast cancer detection after an initial validation in breast cancer cell lines and a small cryoconserved tissue cohort." (PMID 31741713, 2019). "Basal-like breast cancers frequently show low methylation levels of tumor suppressor genes, single CpGs of SPAG6, PER1, NKX2-6 and ITIH5 however showed a higher methylation frequency in this molecular breast cancer subtype (59%, 42%, 52% and 41%, respectively)." (PMID 31741713, 2019). "A combination of SPAG6 and NKX2-6 revealed a sensitivity of 27% for breast cancer detection (cut-off methylation 6.9%, 85% specificity), which could be increased to 31% using a combination of SPAG6 and PER1 (cut-off 7.7%, 85% specificity)." (PMID 31741713, 2019). "Therefore, markers were tested in a plasma cohort, achieving a 64% sensitivity for breast cancer detection using SPAG6, PER1 and ITIH5." (PMID 31741713, 2019). "A separate study also showed that PER1, 2, and 3 exhibited deviant protein expressions in 55 resected breast cancer tissue sections, when compared with adjacent non-cancerous tissue samples." (PMID 29780357, 2018). "Additionally, the deregulated expression of the circadian related genes PER1, PER2 and PER3 in breast cancers has been studied." (PMID 25041817, 2014). "Similarly, inhibition of PER1 alters expression of key cell cycle regulators, by interacting with checkpoint proteins ATM and Chk2, and Per1 overexpression can reduce proliferation in colon, lung and breast cancer cell lines." (PMID 27590298, 2016). "Breast cancer patients showed a non-significant higher methylation frequency for SPAG6 (mean of 6.6% in benign controls versus 8.4% in breast cancer cases, p = 0.2536), PER1 (2.6% versus 4.8%, p = 0.5792), NKX2-6 (1.3% versus 2.9%, p = 0.1898) and ITIH5 (6.8% versus 5.9%, p = 0.9343)." (PMID 31741713, 2019). "However, increases in SPAG6, PER1, NKX2-6 and ITIH5 promoter methylation may not be confined to breast cancer and therefore needs to be tested in non-breast cancer patients such as colorectal- and lung cancer patients, the second and third most common cancers in women." (PMID 31741713, 2019).
glioma (33 papers, 2012 to 2025). A benign or malignant brain and spinal cord tumor that arises from glial cells (astrocytes, oligodendrocytes, ependymal cells). "In a study, researchers observed Per1 overexpression and detected a variant of Per1, rs2289591, which was found to be linked with glioma risk and mortality in patients with high-grade glioma." (PMID 40495887, 2025). "It was also observed that Per1 exhibits a tumor suppressive role in gliomas and the expression of Per1 is linked with increased x-ray sensitivity and cell cycle arrest." (PMID 40495887, 2025). "For example, a genetic variant of PER1 has been associated with overall glioma risk, and decreased PER1 mRNA and protein has been observed in HGGs when compared to lower-grade gliomas (LGG)." (PMID 32631383, 2020). "We previously reported that Per1 and Per2 expression abnormalities are associated with glioma occurrence." (PMID 27036047, 2016). "In our previous study, we reported that Per1 and Per2 expression abnormalities are associated with glioma occurrence." (PMID 27036047, 2016). "Our former study has showed that Per1 and Per2 expression abnormalities can be associated with the occurrence of glioma." (PMID 25760074, 2015). "In addition, deregulation in the expression of Per1 facilitated gliomas in proliferation and survival, as this was linked with a disturbance of the clock activity." (PMID 40495887, 2025). "Abnormalities in Per1 and Per2 expression are associated with the occurrence of gliomas." (PMID 28620312, 2017). "In addition, high expression of Per1 and Per2 in glioma tissue was associated with increased sensitivity to x-irradiation." (PMID 25760074, 2015). "In glioma cells and familial breast tumors, Per1 and Per2 expression levels were significantly reduced compared to normal cells or tissues." (PMID 41142939, 2025). "PER1 plays an important role in various tumors, such as cholangiocarcinoma, glioma, oral squamous cell carcinoma, nasopharyngeal carcinoma, prostate cancer, and gastric cancer." (PMID 41451215, 2025). "Expression of Per1 was linked with the radiosensitivity of gliomas in culture; the downregulation of Per1 weakened the radiosensitivity of U343 glioma cell lines, which resulted in reduced apoptosis of irradiated tumor cells." (PMID 40495887, 2025). "Normal tissues showed around 24 h periodicity on Per1 expression, while gliomas showed a 12-h periodicity." (PMID 40495887, 2025). "It is noteworthy that the expression of PER1, PER2, PER3 is also downregulated in high-grade gliomas and associated with increased proliferation and survival of glioma cells." (PMID 36796229, 2023). "PER1 downregulation has been observed in many tumors, including breast, prostate, glioma and colorectal cancers, giving us confidence in this pan-cancer analysis." (PMID 36321857, 2022). "In an animal model of brain glioma, when radiotherapy was administered during the peak of Per1 or Per2 expression, the apoptosis rate of glioma cells was greater." (PMID 35877357, 2022). "This study suggested that the deregulation in PER1 expression allows glioma cells to proliferate and survive, as this was related to a disruption of the clock function." (PMID 34361055, 2021). "The regulation of PER1 mRNA by IRE-1α is a key molecular event that is capable of controlling glioma angiogenesis, invasion, and growth." (PMID 32195174, 2020). "To this end, we transfected A172 glioma cells with siRNA for PER1 and PER2 before cell synchronization." (PMID 33086741, 2020). "Downregulation of the circadian genes encoding CRY2, PER1, PER2, PER3, CLOCK, REV-ERBβ, ROR-α and ROR-β was associated with significantly higher mortality rates in the glioma cohort, hinting at possible tumor suppressor roles." (PMID 32631383, 2020).
glioma (continued). "Where the mRNA and protein levels of PER1 were significantly reduced in higher grade gliomas relative to low grade ones." (PMID 32195174, 2020). "In conclusions, it can be concluded from our present study that the downregulation of PER1 can decrease the sensitivity of U343 glioma cells exposed to X-ray irradiation and reduce apoptosis." (PMID 31350984, 2019). "Based upon previous studies, we examined the role of PER1 in the cellular response to X-ray-induced DNA damage in the human glioma U343 cell model." (PMID 31350984, 2019). "In this study, we focused on the role of PER1 in DNA damage, apoptosis and radiosensitivity of glioma cells induced by X-ray irradiation." (PMID 31350984, 2019). "Having demonstrated that lentiviral-mediated RNA interference technology was an effective inhibitor of PER1 expression, subsequent experiments utilized this technology to examine the role of PER1 in glioma cells subjected to low-dose X-ray irradiation." (PMID 31350984, 2019). "In contrast, in the glioma tissues, the Per1 mRNA level peaked at ZT4, it was low at ZT12, then it hit a second peak around ZT16 and a second trough around ZT24." (PMID 25760074, 2015). "In this research, we demonstrated that the expression of the clock oscillatory genes Per1 and Per2 shows a circadian rhythm in both glioma and normal brain tissue." (PMID 25760074, 2015). "In glioma tissue, the levels of Per1 and Per2 mRNA were significantly higher in the irradiated group than in the control group when Per1 and Per2 expression was elevated, i.e. at ZT4 for Per1 (t = –4.464, p < 0.001) and ZT0 for Per2 (t = –2.407, p < 0.05)." (PMID 25760074, 2015). "We measured cell proliferation in glioma and normal tissues at ZTs when Per1 and Per2 mRNA levels were high and low, following irradiation with a single dose of x-radiation (15 Gy)." (PMID 25760074, 2015). "We detected apoptosis in glioma and normal tissue after irradiating animals at times when Per1 and Per2 mRNA levels were high and low." (PMID 25760074, 2015). "Future research should focus on the detailed mechanisms by which Per1 and Per2 regulate the expression of genes related to cell proliferation and apoptosis in gliomas." (PMID 25760074, 2015). "We x-irradiated normal and glioma tissue at times when Per1 and Per2 mRNA levels were high and low in gliomas." (PMID 25760074, 2015). "We observed that Per1 and Per2 mRNA levels in irradiated glioma tissue were significantly higher than in untreated glioma." (PMID 25760074, 2015). "We used real-time RT-PCR to measure Per1 and Per2 mRNA levels in glioma and normal tissues after treatment with ionizing radiation (15 Gy)." (PMID 25760074, 2015). "We measured the expression of Per1 and Per2 mRNA over a period of 24 h in both normal and glioma tissue from rats." (PMID 25760074, 2015). "The expression of Per1 and Per2 in glioma tissue shows a period of approximately 12 h, but in normal tissue it shows a period of approximately 24 h." (PMID 25760074, 2015). "We found differences in the circadian expression, and we observed that in glioma tissue, Per1 and Per2 expression was positively correlated with apoptosis and negatively correlated with proliferation." (PMID 25760074, 2015). "In a similar manner, increased Per1 expression is linked with elevated radiosensitivity in gliomas in rats, whereas this finding was not confirmed in non-tumor tissues." (PMID 40495887, 2025).
glioma (continued). "A decreased level of Per1 expression has also been reported in high-grade gliomas." (PMID 40495887, 2025). "For example, glioma, hepatocellular carcinoma, head and neck squamous cell carcinoma, myeloid leukemia, colorectal, pancreatic, gastric, oral, breast, and non-small-cell lung malignancies all have changed expression levels of PER1, PER2, and PER3." (PMID 38892035, 2024). "Furthermore, in the human glioma cell line, U251, we observed reduced PER1 expression upon iron limitation by deferoxamine (DFO; iron chelator) or endogenous overexpression of FPN1." (PMID 38385622, 2024). "Interestingly, Per1 expression was related to the radiosensitivity of gliomas in culture; Per1 downregulation attenuated U343 glioma cell radiosensitivity, decreasing the apoptosis of irradiated tumor cells." (PMID 34361055, 2021). "Similar results recently showed a reduction in PER1 expression in high-grade gliomas." (PMID 34361055, 2021). "However, glioma tissues evidenced a 12-h periodicity on Per1 expression while normal tissues displayed oscillations with a period close to 24 h." (PMID 34361055, 2021). "Circadian genes may potentially influence glioma survival as the overexpression of PER1 and PER2 was found to inhibit the growth and increases apoptosis in tumor cells." (PMID 32195174, 2020). "Furthermore, abnormalities in expression of PER1 and PER2 are associated with the occurrence of glioma." (PMID 32195174, 2020). "PER1, another period isoform, may have a role in radiation-induced apoptosis and DNA damage in gliomas, as downregulation of PER1 attenuated DNA damage in U343 glioma cells." (PMID 32631383, 2020). "This may have consequences for glioma treatment as decreased levels of PER1 have been observed in HGGs and this may make tumor cells less susceptible to apoptosis and other damaging effects from ionizing radiation." (PMID 32631383, 2020). "However, PER1/PER3 expression in C6 glioma cells deemed unresponsive to Ca2+- influx stimulation, meaning that the C6 circadian oscillation got detached from neighboring neuronal signaling." (PMID 32195174, 2020). "However, PER1/2 expression correlates with WHO grading of glioma, being downregulated in glioma tissue compared to normal brain tissue." (PMID 33114365, 2020). "Many of the core circadian rhythm PAS factors, including the period (PER) genes, are downregulated in breast, colorectal, prostate, glioma and non-small cell lung cancer in humans; moreover, it has been suggested that PER1 and PER2 function as tumor suppressors." (PMID 28177907, 2017). "Additionally, decreased Per1 and Per2 expression increases the efficacy of radiotherapy against glioma by promoting apoptosis." (PMID 27036047, 2016). "Our results suggest that Per1 and Per2 expression may increase the efficacy of radiotherapy against glioma by promoting apoptosis." (PMID 25760074, 2015). "In addition, the high expression of Per1 and Per2 sensitized the glioma cells to x-irradiation, promoting apoptosis as a result." (PMID 25760074, 2015). "To determine whether changes in Per1 and Per2 expression may affect the radiation sensitivity of glioma, we measured proliferation and apoptosis of glioma cells when rats were x-irradiated at times when Per1 and Per2 mRNA levels were high and low." (PMID 25760074, 2015). "This suggests that the low proliferation and high apoptosis associated with low Per1 expression in glioma may result from the coincidence at ZT12 of high Per2 expression and low Per1 expression." (PMID 25760074, 2015). "In glioma tissue, Per1 expression showed a period of approximately 12 h." (PMID 25760074, 2015).
glioma (continued). "To test whether circadian expression of Per1 and Per2 may be involved in glioma growth, we analyzed expression patterns in both glioma and normal brain tissue." (PMID 25760074, 2015). "However, when we compared the levels at ZT12, when Per1 expression was low in glioma, the level in the irradiated group was significantly higher than in the control group (t = –5.135, p < 0.001)." (PMID 25760074, 2015). "This suggests that x-irradiation can increase the expression of Per1 and Per2 in glioma tissue." (PMID 25760074, 2015). "Moreover, other researchers have found lower PER1/2 expression in in higher-grade gliomas." (PMID 39001398, 2024). "Besides the downregulation of Per1 levels observed in gliomas, these results suggest that tumor cells may display aberrant oscillations on Per1 expression, influencing cell proliferation and tumor survival." (PMID 34361055, 2021). "The results showed that the apoptosis rate of glioma cells was higher when radiotherapy was administered at the peak of Per1 or Per2 expression, indicating that clock genes could act as molecular targets that regulate chronotherapy efficacy and promote personalized therapeutic effects." (PMID 34966277, 2021). "For Per1 expression, disturbances on rhythmic expression of Cry2 were observed in glioma tissues with a period of 8 h compared to 24-h periodicity displayed by normal brain samples suggesting that an altered rhythmic expression of Cry2 influences sensitivity to irradiation on gliomas cells." (PMID 34361055, 2021). "Furthermore, the circadian genes Per1 and Per2 increase the radiosensitivity of gliomas in vivo." (PMID 27036047, 2016). "On the contrary, PER1/2 show lower expression in higher gliomas, and CRY1/2 show lower expression in gliomas compared to normal tissue." (PMID 37400829, 2023). "To investigate the role of CCGs in all grades of glioma, including grade 2-4, we firstly analyzed the differential expression of CCGs in glioma grade and found that 11/13 CCGs, except for CLOCK and PER1, were recognized as DEGs in TCGA and CGGA, respectively." (PMID 35832846, 2022). "PER1 and PER2 oscillation profiles were found to vary between both glioma and normal brain tissue, albeit being within the circadian range in both." (PMID 32195174, 2020). "Experimental evidence from our previous studies indicated that the expression of PER1 and PER2 closely correlated with the incidence and development of glioma." (PMID 31350984, 2019). "In normal tissue, we compared Per1 mRNA levels at ZT4, when Per1 expression was high in glioma tissue." (PMID 25760074, 2015). "It was observed that as compared to adjacent non-glioma cells, period CC (Per) genes including Per1 and Per2 were found to be underexpressed in glioma cells." (PMID 40495887, 2025). "A lower-level expression of Per1 was detected in high-grade glioma cell lines than in adjacent non-tumor-bearing tissues." (PMID 40495887, 2025). "Using the U251 glioma cell model, we also observed rhythmic transcriptions of the clock genes, including BMAL1, CLOCK, CRY1, and PER1, which adds novel evidence that the biological clock also functions in vitro, suggesting that this cell line is suitable for biological rhythm research." (PMID 38385622, 2024). "Early studies from Wang’s laboratory showed that PER1 expression is lower in high-grade gliomas than in the surrounding non-tumor tissues." (PMID 34361055, 2021). "Similarly, high expression of Per1 correlated with increased radiosensitivity in gliomas cells in a rat model, while this phenomenon was not evidenced in non-tumor tissues." (PMID 34361055, 2021).
glioma (continued). "Altered expression of PER1, PER2 and/or PER3 have been reported in colorectal, pancreatic, gastric, oral, breast, prostate, bladder, renal, and non-small cell lung cancers, as well as in glioma, hepatocellular carcinoma, head and neck squamous cell carcinoma and myeloid leukemia." (PMID 33114365, 2020). "Expression of PER1 and PER2—genes involved in the negative limb of the circadian clock—is found to be lower in glioma cells compared to the surrounding non-cancer tissue." (PMID 38173841, 2023).